LGALS1 (galectin 1)
Diseases named in the same sentence as LGALS1 in open-access papers (continued):
Sharing a sentence is not in itself a finding about the gene and the disease.
hepatocellular carcinoma (continued). "Furthermore, galectin-1 inhibitor TDG can increase the anti-tumor activity of cisplatin to hepatoma-bearing mice." (PMID 26859293, 2016). "In this present study, we did find increased mitophogy via immunostaining by galectin-1 in cisplatin-treated hepatoma cells, suggesting that galectin-1-triggered autophagy may help cells to eliminate damage mitochondria and resist chemotherapy drugs." (PMID 26859293, 2016). "Thus our findings have uncovered a new role of galectin-1 in promoting the chemoresistance in hepatocellular carcinoma, and so represent a promising approach to vanquish the chemoresistance acquired towards the cisplatin treatment." (PMID 26859293, 2016). "Significant up-regulation of BNIP3 was induced by galectin-1 in hepatoma cells." (PMID 26859293, 2016). "This suggests that high levels of galectin-1 in the hepatoma microenvironment during the cisplatin treatment could facilitate the chemoresistance of cancer cells." (PMID 26859293, 2016). "Galectin-1-induced autophagy could facilitate cisplatin resistance in hepatocellular cancer." (PMID 28546799, 2017). "Hence we investigated whether soluble galectin-1 is able to induce the up-regulation of BNIP3 in hepatoma cells." (PMID 26859293, 2016). "Lectin galactoside-binding soluble 1 (LGALS1, also named galectin-1) has been recognized to support EMT and metastasis in hepatocellular carcinoma." (PMID 33435156, 2021). "In fact, galectin-1 treatment is able to induce an upregulation of BNIP3 and a down regulation of m-TOR in hepatoma cells." (PMID 31295873, 2019). "In human cancers, including hepatocellular carcinoma (HCC), galectin-1 (Gal-1) is often found to be overexpressed." (PMID 31640796, 2019). "We have also found that the soluble galectin-1 inhibitors such as lactose and TDG were successfully able to sensitize the hepatocellular carcinoma cells towards the cisplatin treatment." (PMID 26859293, 2016). "Furthermore, recent studies indicated that Galectin-1 triggered EMT in human gastric cancer and hepatocellular carcinoma cells, thereby promoting tumor invasion and metastasis." (PMID 29156810, 2017). "Subsequently, wild type or Atg5 knock down hepatoma cells were pretreated with or without galectin-1, and then with cisplatin, after which their chemoresistance was evaluated." (PMID 26859293, 2016). "In hepatocellular carcinoma (HCC) which is associated with chronic inflammation and fibrosis, galectin-1 deficiency with increased osteopontin and S100A4 expressions could amplify inflammatory processes, thereby exacerbating the liver injury and fibrosis in a mouse model of HCC." (PMID 36873388, 2023). "In the inflammation category, Lgals1 (Galectin-1), an important immune response modulator and biomarker for hepatocellular carcinoma (HCC) was also markedly increased in SO-HFD but not HFD, as were Abcd2, Cd63, Ly6d and Ubd." (PMID 26200659, 2015).
lung carcinoma (26 papers, 2014 to 2025). "Murine breast, colon, and Lewis lung cancer cells with silenced Galectin-1 showed decreased lung metastasis, which was associated with increased T-cell numbers and reduced angiogenesis." (PMID 24592356, 2014). "Galectin-1 derived from lung cancer is one of the culprits of DC cell incapacitation, and it has been demonstrated that this phenomenon is mediated by the galectin-1-CAF axis and mainly associated with the tryptophan 2,3-dioxygenase (TDO2)/kynurenine axis in CAFs." (PMID 40244052, 2025). "This speculation is further supported by our previous research demonstrating that when KIT or PTEN cancer-critical genes are mutated in lung cancer, galectin-1 levels are elevated." (PMID 38539500, 2024). "For instance, the survival rate of patients with gingival squamous cell carcinoma, lung cancer and colon cancer with strong LGALS1 expression was more significantly associated with a poorer outcome than that of patients with LGALS1 negative or weak expression 23-25." (PMID 33854625, 2021). "In line with our results, a notable overexpression of galectin-1 levels was observed in lung cancer tissues especially adenocarcinoma which promotes lung cancer progression, invasion migration and metastasis." (PMID 40022036, 2025). "Galectin-1 has been shown to promote lung cancer metastasis by increasing levels of Notch and its ligand, Jagged2, while enhancing AKT activation, promoting tumorigenesis and invasiveness, and is associated with a poor prognosis in lung adenocarcinoma." (PMID 38539500, 2024). "In our study, we have analyzed galectin-1, galectin-3, and galectin-9, as these are among the most extensively studied galectins in the context of lung cancer." (PMID 38539500, 2024). "The biochemical functions of galectins are of interest in oncology with galectin-1, -3, -4, -7, -8, and -9 being the most extensively studied in lung cancer." (PMID 38539500, 2024). "Recently, it was found that inhibition of Galectin-1 in tumor cells was related to elevated sensitivity to CDDP in lung cancer, neuroblastoma and epithelial ovarian cancer 36-38." (PMID 37215991, 2023). "That maturation of DCs was suppressed by galectin-1 was also demonstrated in neuroblastoma and lung cancer." (PMID 37047471, 2023). "Here, we show that SGT-53 can restore effective immune responses against lung cancer cells by reducing immunosuppression through galectin-1 (Gal-1) pathway previously shown to contribute to lung cancer progression." (PMID 36359830, 2022). "Galectin-1 knockdown was previously reported to sensitize lung cancer cells to platinum-based chemotherapy." (PMID 32486344, 2020). "Suppression of galectin-1 can sensitize lung cancer cells to cisplatin, while increase the expression of galectin-1 in epithelial ovarian cells can enhance their resistance to cisplatin." (PMID 28842515, 2017). "Our previously reported that galectin-1, serves as a specific cancer-derived factor to inhibit DC differentiation and function in lung cancer." (PMID 27050278, 2016). "By expanding upon previous studies, results of the present study show that galectin-1 is involved in lung cancer-mediated changes in switching switch of fibroblasts to myofibroblasts, and Trp metabolism." (PMID 27050278, 2016). "Knockdown of galectin-1 loses the inductive effect of CL1-5 cancer cells on TDO2 expression and Kyn production in LCAF, suggesting that lung cancer-derived galectin-1 is responsible for TDO2 induction in LCAF." (PMID 27050278, 2016). "The inhibitory effect of CAF is mediated by elevated levels of Kyn, which is triggered by lung cancer-derived galectin-1." (PMID 27050278, 2016). "High expression of Galectin-1 in lung cancer cell lines, as well as in human tumor tissues, alters the phenotype of monocyte-derived dendritic cells and impairs T-cell response, concomitant with increased presence of regulatory T-cells (Tregs)." (PMID 24592356, 2014).
lung carcinoma (continued). "Our recent studies found that lung cancer cells secret galectin-1, which promotes its migration, invasion, and EMT." (PMID 25937967, 2014). "More recently, elevated levels of galectin-1 expression were found to promote lung cancer progression and chemoresistance while increased galectin-4 expression was shown to predict lymph node metastasis in adenocarcinoma of the lung." (PMID 25259711, 2014). "The enhanced infiltration of CD11c+ dendritic cells in human lung cancer samples has been recapitulated in a mouse model, which was completely omitted after transplantation of Galectin-1 silenced tumor cells." (PMID 24592356, 2014). "In a lung cancer study, it was found that the impaired differentiation and function of DCs was due to tryptophan degradation, which was caused by both CAF-released IDO1 and lung-cancer-derived galectin-1-induced tryptophan 2,3-dioxygenase (TDO2)." (PMID 40805183, 2025). "In addition, lung cancer-derived galectin-1 was found to elevate the frequency of CD4+CD25+FOXP3+ Tregs besides diminishing Th1 cytokines and increasing IL-10 in MDDCs." (PMID 37047471, 2023). "The distinct distribution of galectin-1 in human cells versus mouse cells, and the nature of the cell line, a human lung cancer cell line versus a mouse neural cell line may contribute to the difference." (PMID 36404916, 2022). "Similarly to galectin-3, galectin-1 has recently been identified to promote lung cancer metastasis by potentiating integrin α6β4 and Notch1/Jagged2 signaling." (PMID 28860622, 2017). "Moreover, we also demonstrate that lung cancer-derived galectin-1 contributes to the upregulation of TDO2 in CAF through an AKT-dependent pathway." (PMID 27050278, 2016). "Furthermore, expression profiling on different lung cancer cell lines confirmed that expression was confined to galectin-1, -3, -4, -7, -8, and -9." (PMID 25259711, 2014). "How Galectin-1 contributes to immune-suppression in tumors has been delineated in lung cancer." (PMID 24592356, 2014). "All these findings show that galectin-1, galectin-3, and galectin-8 are the most abundantly expressed galectins while the expression of galectin-4, galectin-7, and galectin-9 is relatively low, both in tumor tissues and in different lung cancer cell lines." (PMID 25259711, 2014). "On the other hand, our previous studies found that galectin-1 secreted by lung cancer cells may promote differentiation of monocyte to specific TADCs, which can secrete amphiregulin to enhance cancer cell proliferation, EMT, and therefore invasiveness." (PMID 25937967, 2014). "Furthermore, galectin-1 expression is elevated in lung cancer tissue as compared to normal lung." (PMID 25259711, 2014). "Another study of lung cancer indicated that both CAF-released IDO1 and tryptophan 2,3-dioxygenase (TDO2) induced by lung cancer-derived galectin-1 are responsible for the impaired differentiation and function of DCs through the degradation of tryptophan." (PMID 34635121, 2021). "Taken together, our data identify the feedback loop, consisting of cancer-derived galectin-1 and CAF-producing kynurenine, that sustains lung cancer progression." (PMID 27050278, 2016).
gastric cancer (25 papers, 2013 to 2026). A primary or metastatic malignant neoplasm involving the stomach. "High expression of Galectin-1 (Gal-1) was associated with increased invasion and metastasis of gastric cancer cells and a poorer prognosis and survival, as well as increased lymph node metastasis and tumor invasion depth in gastric cancer patients." (PMID 34572373, 2021). "Galectin-1 released by fibroblasts associated with gastric cancer, promote gastric cancer cells EMT, by binding to integrins and activating the hedgehog pathway." (PMID 34356834, 2021). "In summary, our findings reveal that PITX2 is significantly linked to unfavorable outcomes in gastric cancer and modulates the expression of lysosomal exocytic genes, including MCOLN1 and RAB3A, which enhance the secretion of LGALS1 and IGFBP7." (PMID 40995693, 2025). "Through the survival analysis of galectin-1 expression, its value as a prognostic factor has been established in prostate, ovarian, and stomach cancers, and high galectin-1 expression has been correlated with poor prognosis." (PMID 39996781, 2025). "Functional studies utilizing LGALS1 knockdown in the HGC-27 gastric carcinoma cell line demonstrated that silencing Gal-1 significantly suppressed cellular proliferation, as well as migratory and invasive capacities." (PMID 40710343, 2025). "The overexpression of galectin-1 is also correlated with lymph node and distant metastasis in gastric cancer and advanced staging." (PMID 37371482, 2023). "In gastric cancer cells overexpressing galectin-1, EMT was mediated through a sphingosine-1-phosphate receptor 1-dependent mechanism, resulting in increased malignancy." (PMID 34356834, 2021). "One such factor is galectin-1, which shows increased expression in CAMs and was shown to enhance gastric cancer cell migration and invasion by upregulating integrin-β1 expression." (PMID 30813438, 2019). "Recently, we showed a similarly increased expression of annexin-A1 and galectin-1 in chronic gastritis and in gastric cancer, evidencing deregulation in the expression of these proteins during the initial step of gastric carcinogenesis." (PMID 24719523, 2014). "Studies on annexin-A1 and galectin-1 in gastric cancer and precancerous lesions are few and reveal contradictory results." (PMID 24719523, 2014). "Notably, elevated levels of LGALS1 and IGFBP7 were linked to an adverse survival prognosis in individuals with gastric cancer from Kaplan‐Meier Plotter database." (PMID 40995693, 2025). "Galectin-1 (Gal-1) can be used as an indicator of poor survival in human gastric cancer patients." (PMID 29899399, 2018). "In addition, CAM-derived galectin-1 is also known to promote angiogenesis in gastric cancer." (PMID 30813438, 2019). "Clinically, elevated expression of HOXA1, PITX2, MCOLN1, RAB3A, LGALS1, and IGFBP7 constitutes a prognostic signature correlating with poor outcomes of gastric cancer patients." (PMID 40995693, 2025). "High expressions of galectin-1 and GRP78 also reflect poor overall survival in gastric cancer patients." (PMID 37371482, 2023). "In fibroblasts, galectin-1 induced EMT through the TGF-β1/Smad signaling pathway thereby promoting invasion and metastasis of gastric cancer cells." (PMID 36017312, 2022). "In gastric cancer fibroblasts (CAF), galectin-1 stimulated high expression by upregulating β1-integrin and induced EMT through the Hedgehog signaling pathway, which promoted migration and invasion of cancer cells." (PMID 36017312, 2022). "Therefore, the aim of this study was to investigate the relative expression levels of ANXA1 and LGALS1 mRNA by quantitative real-time PCR (qPCR) and the expression of both proteins by immunohistochemical assay in inflammatory gastric lesions such as chronic gastritis compared to gastric cancer." (PMID 23431236, 2013).
gastric cancer (continued). "Mechanistically, HOXA1‐PITX2 complex facilitates the expression of mucolipin 1 (MCOLN1) and RAS‐related protein Rab‐3A (RAB3A), which drive lysosomal exocytosis of galectin‐1 (LGALS1) and insulin like growth factor binding protein 7 (IGFBP7) from senescent gastric cancer cells." (PMID 40995693, 2025).
melanoma (25 papers, 2005 to 2025). A malignant, usually aggressive tumor composed of atypical, neoplastic melanocytes. "LGALS1 has been previously implicated in pancreatic ductal adenocarcinoma, clear cell renal cell carcinoma, cervical cancer, and malignant melanomas." (PMID 35687691, 2022). "In melanoma, galectin 1 has been thought to cause resistance of melanoma cells to cytotoxic stimuli and to enhance angiogenesis." (PMID 29666124, 2018). "When miR-22-3p is overexpressed in WM-266-4 melanoma cells, the cell viability is decreased, the expression levels of LGALS1, VIM, and SNAI2 are decreased, the expression level of CDH1 is increased, and cell apoptosis is increased." (PMID 39684214, 2024). "As a key promoter of angiogenesis and fibrosis, LGALS1 inhibits tumor immune response and is highly expressed in melanoma and head and neck cancer." (PMID 38099574, 2023). "In the current study, we address the potential of such an approach by exploring the efficacy of galectin-1 vaccination in melanoma." (PMID 35018481, 2022). "MCAM has been reported to be recognized by galectin-1 in melanoma cells, and their interaction increased melanoma cell migration." (PMID 36291660, 2022). "In summary, our work shows that Galectin-1 triggers an autocrine NRP1-dependent pathway in melanoma cells, driving adaptive refractoriness to BRAF inhibitors." (PMID 32784465, 2020). "In summary, we found that the activation of Galectin-1/NRP1 autocrine signaling is a new mechanism conferring independence from BRAF kinase activity to oncogene-addicted melanoma cells." (PMID 32784465, 2020). "This was confirmed in two distinct melanoma cell lines, where we found that Galectin-1 was driving the refractoriness to BRAF-targeted therapy." (PMID 32784465, 2020). "The amount of extracellular of galectin-1 is altered in a variety of cancer cell types, including melanoma, ovarian, lung, prostate, bladder, thyroid, pancreatic, head-neck, cervical, uterine, and colorectal cancers." (PMID 27649167, 2016). "Recently it has been shown that depletion of galectin-1 can extend the life of melanoma bearing mice." (PMID 26859293, 2016). "Experimental evidence also suggests that Galectin-1 expressed on various tumor-cell types including hepatocellular carcinoma, melanoma, ovarian, and prostate cancer cells mediates tumor-cell adhesion to the extracellular matrix." (PMID 24592356, 2014). "Accumulating evidence indicate that tumor-derived Galectin-1 contributes to immunosuppressive activity in different tumors, including lung and pancreatic carcinoma, melanoma, and neuroblastoma." (PMID 24592356, 2014). "Galectin-1 expression by melanoma cells induced apoptosis of tumor-specific effector T-cells, and Galectin-1 inhibition allowed generation of a tumor-specific T1 response." (PMID 24592356, 2014). "Expression of galectin-1 has been well documented in many different tumour types including astrocytoma, melanoma and prostate, thyroid, colon, bladder and ovary carcinomas." (PMID 15785741, 2005). "Galectin 1 (Gal-1) is an important member of the galectin family, acting as a central regulator in immune cells, tumor immune evasion, metastasis, angiogenesis, and therapy resistance, especially in melanoma." (PMID 41918780, 2025). "Thus, Galectin-1/NRP1 signaling represents a druggable mechanism controlling adaptive resistance to therapy in melanoma cells." (PMID 32784465, 2020). "A similar study identified six more proteins overexpressed in melanoma cell lines compared to normal melanocytes, i.e., galectin-1, inosine-5′-monophosphate dehydrogenase 2, serine/threonine-protein phosphatase 2A 65 kDa regulatory subunit A α isoform, protein DJ-1, cyclophilin A and cofilin-1." (PMID 32331267, 2020). "In addition, galectin-1 can also mediate homotypic cell aggregation of human melanoma cells in a carbohydrate-dependent manner." (PMID 15785741, 2005).
melanoma (continued). "BMSC-derived exosomes coated with miR-22-3p via transfection inhibit the proliferation of human melanoma cells by suppressing EMT and targeting galectin 1 (LGALS1)." (PMID 37242707, 2023). "By analyzing an accessible small series of paired melanoma samples, we found that a relatively poorly studied NRP1-ligand, Galectin-1, is induced upon the onset of resistance to BRAF inhibitors." (PMID 32784465, 2020). "The combined blockade of Galectin-1 and NRP1 in drug-resistant melanoma cells restored BRAF-addiction and sensitivity to therapy." (PMID 32784465, 2020). "Similar to steady-state, cues derived from NLTs are likely to prime Treg cells located in the draining LNs, as indicated by a higher percentage of cells expressing Batf, Lgals1, Id2, and other NLT markers in melanoma." (PMID 30737144, 2019). "Dose-dependent binding of galectin-1 to laminin and fibronectin in cell–ECM adhesion has been reported in melanoma and ovarian cancer cell lines." (PMID 27649167, 2016). "The hypoxia-sensitive protein Galectin-1 that is upregulated in melanoma, offers a cytoprotective effect to various anticancer drugs via modulation of the UPR in melanoma cells." (PMID 26927180, 2016). "In full concordance, Galectin-1 expression was also significantly increased in A375 and SK-MEL-28 melanoma cells that developed resistance in culture upon prolonged treatment with escalating concentrations of the BRAF inhibitor PLX-4720, thus recapitulating the process occurring in patients." (PMID 32784465, 2020). "Besides, Ocoxin reduces the secretion of proinflammatory mediators LGALS1, OPN, CCL5, and CCL9 chemokines by melanoma cells, which could result in a reduction of the recruitment and differentiation of mesenchymal stem cells into CAFs and decreased resistance to anticancer drugs of cancer cells." (PMID 33669949, 2021).